RGS19 (regulator of G protein signaling 19)
Description:
Inhibits signal transduction by increasing the GTPase activity of G protein alpha subunits thereby driving them into their inactive GDP-bound form. Binds to G-alpha subfamily 1 members, with the order G(i)a3 > G(i)a1 > G(o)a >> G(z)a/G(i)a2. Activity on G(z)-alpha is inhibited by phosphorylation and palmitoylation of the G protein.
Synonyms: GAIP; RGSGAIP
Tractability: Antibody: its Gene Ontology location is reachable by antibodies, with high confidence. PROTAC: ubiquitination databases record sites on it; its protein half-life has been measured; a small molecule that binds it is known.
Target class: Enzyme
Gene: Protein-coding gene on chromosome 20 (64,073,181 to 64,079,988, reverse strand). Ensembl gene ENSG00000171700.
Subcellular location: Membrane
Subcellular location (Human Protein Atlas): Cell Junctions; Nucleoli fibrillar center
Pathways (Reactome):
Signal Transduction: G alpha (i) signalling events; G alpha (q) signalling events; G alpha (z) signalling events
Gene Ontology:
Molecular function: protein binding; GTPase activity
Biological process: G protein-coupled receptor signaling pathway; negative regulation of G protein-coupled receptor signaling pathway; small GTPase-mediated signal transduction
Cellular component: cell junction; cytoplasmic side of plasma membrane; Golgi apparatus; membrane; plasma membrane
Genetic constraint (gnomAD): Loss-of-function variants: 11 observed, 23.16 expected, observed/expected ratio (o/e) 0.47, 90% interval 0.3 to 0.79. The upper end of that interval is the gene's LOEUF score, 0.79, which puts it in group 3 of 6, group 1 being the genes least tolerant of losing a copy. Missense variants: 256 observed, 298.82 expected, observed/expected ratio (o/e) 0.86, 90% interval 0.77 to 0.95. Synonymous variants: 130 observed, 124.04 expected, observed/expected ratio (o/e) 1.05, 90% interval 0.91 to 1.21.
Homologues: Orthologues: chimpanzee RGS19 (100% identical), macaque RGS19 (99% identical), dog RGS19 (92% identical), guinea pig RGS19 (92% identical), mouse Rgs19 (90% identical), rat Rgs19 (89% identical), pig RGS19 (74% identical), tropical clawed frog rgs19 (65% identical), zebrafish rgs19 (58% identical). Paralogues in human: RGS20 (59% identical), RGS17 (52% identical), RGS3 (35% identical), RGS8 (30% identical), RGS12 (29% identical), RGS18 (29% identical), RGS11 (29% identical), RGS4 (29% identical), RGS16 (29% identical), RGS13 (28% identical), RGS1 (28% identical), RGS2 (28% identical), and 11 more.
Diseases named in the same sentence as RGS19 in open-access papers:
RGS19 is named in the same sentence as 20 diseases in open-access papers, as found by Europe PMC text mining. Sharing a sentence is not in itself a finding about the gene and the disease. The quoted sentences say what the papers report.
ovarian carcinoma (4 papers, 2021 to 2024). A malignant neoplasm originating from the surface ovarian epithelium. "RGS19 is associated with carcinogenesis in several types of cancers, including ovarian cancer, gastric cancer, and prostate cancer." (PMID 38321105, 2024). "In addition, RGS19 has been associated with the carcinogenesis of several other cancers, including ovarian cancer, primary kidney tumor, gastric cancer, prostate cancer and colorectal tumor." (PMID 34482807, 2021). "Moreover, RGS2 and RGS10 are found to inhibit cell proliferation in ovarian cancer, whereas RGS19 gives rise to the opposite effect on ovarian cancer progression." (PMID 37118788, 2023).
colon cancer (3 papers, 2009 to 2018). "Finally, RGS19 has been implicated in the control of autophagy in colon cancer cell lines." (PMID 19208118, 2009). "Studies have shown that RGS19 and GNAI3 are engaged in controlling autophagy in human colon cancer HT-29 cells." (PMID 24751948, 2014).
Encephalopathy (3 papers, 2022 to 2024). Encephalopathy is a term that means brain disease, damage, or malfunction. "Interaction of GNAO1 encephalopathy mutants with RGS19 and Gβγ." (PMID 38874642, 2024).
lung carcinoma (3 papers, 2020 to 2024). "Moreover, expression of RGS19 was lower in leukemia, lung cancer, and lymphoma than in other cancers." (PMID 32903592, 2020). "RGS19 can effectively inhibit Ras-related carcinogenesis in lung cancer." (PMID 32547955, 2020). "Rapid termination of G protein signals by RGS proteins can potentially modulate growth signals and hence promote tumorigenesis, although no clear mechanism of RGS19 in lung cancer was reported." (PMID 39443755, 2024).
non-small cell lung carcinoma (3 papers, 2020 to 2024). A group of at least three distinct histological types of lung cancer, including non-small cell squamous cell carcinoma, adenocarcinoma, and large cell carcinoma. "Previous research in non-small cell lung carcinoma (NSCLC) also supported the role of RGS19 in the cell cycle, as the suppression of tumorigenesis after knocking down RGS19 cell line H1299 suggested that RGS19 can facilitate the process of oncogenesis." (PMID 34482807, 2021).
bladder cancer (2 papers, 2021 to 2023). "The upregulated expression of RGS19 was associated with poor prognosis of bladder cancer patients." (PMID 36611973, 2023). "The results showed that RGS19 was overexpressed in a wide range of tumor, especially bladder cancer." (PMID 34482807, 2021). "We chose RGS19 as a therapeutic target gene in bladder cancer." (PMID 34482807, 2021).
atherosclerosis (1 paper, 2022). A disease characterized by the build-up of fatty material and calcium deposition in the arterial wall resulting in partial or complete occlusion of the arterial lumen. "For example, KPTN and RGS19, both novel genes displaying significant TWAS results for CAD—based on their genetically-modulated expression profiles of liver tissue—also showed significant association with various lipid traits as well as aortic lesion area in the atherosclerosis mouse model." (PMID 35175464, 2022).
kidney cancer (1 paper, 2020). Primary or metastatic malignant neoplasm involving the kidney. "RGS19 expression was higher in bladder, breast, and kidney cancer tissues than in normal tissues." (PMID 32903592, 2020).
vitiligo (1 paper, 2022). Generalized well circumscribed patches of leukoderma that are generally distributed over symmetric body locations and is due to autoimmune destruction of melanocytes. "After experimental verification for several markedly altered candidates, FOS and RGS19 were confirmed to be significantly high in vitiligo lesions, which was in line with the results from our RNA-seq dataset." (PMID 35406685, 2022). "FOS and RGS19 were confirmed to have significant increases in vitiligo patients." (PMID 35406685, 2022). "qRT-PCR confirmed the significant increases in FOS and RGS19 in vitiligo lesions." (PMID 35406685, 2022). "However, the role of RGS19 in the immune response of vitiligo still needs further study." (PMID 35406685, 2022).
cancer (10 papers, 2017 to 2025). A tumor composed of atypical neoplastic, often pleomorphic cells that invade other tissues. "They studied the regulator of G protein signaling family, RGS19, a protein linked to several cancers’ progression." (PMID 38825640, 2024). "cBioPortal and UALCAN analyses indicated that altered P4HB and RGS19 mRNA expression was significantly associated with mutations and clinical characteristics (nodal metastasis and cancer stage)." (PMID 32903592, 2020). "In addition, the expression of RGS19 has been significantly associated with carcinogenesis in various cancers." (PMID 38825640, 2024). "Regulator of G-protein signaling 19 (RGS19) is a multifunctional protein that regulates the progression of various cancers." (PMID 38825640, 2024). "The influence of RGS19 expression on cancer pathogenesis was explored, and pathway analysis and cell models verified its function in the cell cycle." (PMID 34482807, 2021). "We evaluated the abnormally high expression level and effects on the prognosis of RGS19 in many types of cancer through integrated data analysis." (PMID 34482807, 2021). "Given that P4HB and RGS19 are the potential clinical values of ARGs for BUC, we further investigated the clinical significance of P4HB and RGS19 and found that these two genes were closely related to nodal metastasis and cancer stage." (PMID 32903592, 2020). "The transcription levels of P4HB and RGS19 were significantly higher in the tumor tissues than in the non-cancerous bladder tissues in subgroup analyses based on gender, age, cancer stage and nodal metastasis status." (PMID 32903592, 2020). "RGS19 overexpression has been shown to promote cell proliferation through deregulating cell cycle control and enhancing Akt signaling in several types of cancer." (PMID 29796168, 2018). "To clarify whether P4HB and RGS19 were prognostic factors independent of other clinical variables, we performed univariable and multivariable Cox regression analyses with P4HB, RGS19, and clinical features (age, gender, cancer stage, and pathological TNM stage) as covariates." (PMID 32903592, 2020). "These included multitrait colocalization at 6 loci with a consistent direction of effect between CAD and cancer (ABO, PGAP3, ANGPTL4, SREBF1, HAUS6, and SYNJ2BP) and 7 with an opposing direction (CDKN1A, RGS19, CALCRL, SF3A3, LAMC1, MYO9B, and MIA3)." (PMID 40874306, 2025). "Specifically, KDM6B, RGS19, and SMAD3, which belong to beta-catenin binding in the gene ontology, were up-regulated during the process of cancer plasticity." (PMID 35673567, 2022). "The linkage between RGS19, cAMP/CREB pathway and Nm23-H1/2 expression described herein may provide clues to the in vivo effectiveness of cAMP-modifying agents that suppress cancer cell migration." (PMID 29050254, 2017). "Taken together, these results strongly supported the excellent anti-cancer effects of BRD4 inhibition by JQ1 in sunitinib-resistant ccRCC and suggested that SCG5, SPOCD1, RGS19, and ARHGAP22 may be novel direct targets of the epigenetic reader BRD4 in sunitinib-resistant ccRCC." (PMID 29796168, 2018). "More importantly, multivariate Cox proportional hazards regression analysis demonstrated that P4HB, but not RGS19, is an independent and unfavorable BUC biomarker based on clinical characteristics (age, gender, cancer stage, and pathological TNM stage)." (PMID 32903592, 2020).
tumor (8 papers, 2020 to 2024). "The results indicated that increased RGS19 expression was positively associated with increased tumor size (p = 0.014), increased AFP levels (p = 0.003) and advanced TNM stage (p = 0.014)." (PMID 38825640, 2024). "In this study, we discovered that upregulated RGS19 expression is significantly associated with tumor size, AFP level, OS, and PFI in patients with HCC." (PMID 38825640, 2024). "Both bioluminescence imaging and tumor specimen analysis indicated that MYH9 knockdown suppressed the promotive effect of RGS19 overexpression on tumor growth." (PMID 38825640, 2024). "Bioluminescence imaging revealed that RGS19 overexpression promoted tumor growth, while RGS19 knockdown significantly inhibited tumor growth." (PMID 38825640, 2024). "The number of TUNEL-positive cells in the tumor sections was significantly greater in the RGS19-knockout group than in the vector group." (PMID 38825640, 2024). "To further confirm the pivotal role of RGS19 in tumor growth, we established a C57BL/6 HCC mouse model." (PMID 38825640, 2024). "During the development of human solid tumours, RGS19 appears to promote the proliferation of tumour cells in situ while inhibiting the migratory development of tumour cells." (PMID 37924113, 2023). "To elucidate the relevance of P4HB and RGS19 with respect to tumor progression, we further performed a subgroup analysis of multiple BUC clinicopathological features." (PMID 32903592, 2020). "Moreover, both bioluminescence imaging and tumor specimen analysis revealed that tumor volume and weight were decreased by si-β-catenin or si-c-Myc in RGS19-overexpressing cells in vivo." (PMID 38825640, 2024). "The observed effects of Rapamycin on tumor suppression are likely to involve the autophagy process, evidenced by the inhibition of autophagy modulators (TGFβ1, RGS19 and AKT1), autophagosome biogenesis components (AMBRA1, ATG9B and TMEM74) and autophagy byproducts (APP)." (PMID 38276004, 2024). "The expression of regulator of G protein signalling 19 (RGS19), a regulator of the RGS family of G protein signalling pathways, is upregulated in many tumours, including HCC29." (PMID 38321105, 2024). "Based on the data from the TCGA and DepMap databases, comprehensive analysis proved significantly high expression of RGS19 in BLCA, which was related to tumor progression and poor prognosis." (PMID 34482807, 2021). "RGS19 also regulates the cAMP/PKA/CREB pathway and transcriptionally upregulates the tumour metastasis suppressor Nm23, thereby attenuating the migration ability of tumour cells." (PMID 37924113, 2023).
RGS19 also shares sentences with these, for which no sentence is quoted: pancreatic tumor (3 papers); gastric cancer (2); prostate carcinoma (2); colorectal tumor (1); hepatocellular carcinoma (1); leukemia (1); lymphoma (1); melanoma (1); pancreatic cancer (1).